Y_RNA (Y RNA )
Gene: Miscellaneous RNA gene on chromosome 22 (19,045,256 to 19,045,367, forward strand). Ensembl gene ENSG00000206739.
Homologues: Orthologues: chimpanzee Y_RNA (99% identical). Paralogues in human: Y_RNA (91% identical), RNY1 (88% identical), Y_RNA (88% identical), Y_RNA (87% identical), Y_RNA (86% identical), Y_RNA (85% identical), RNY1P11 (84% identical), Y_RNA (84% identical), Y_RNA (83% identical), RNY1P8 (82% identical), Y_RNA (82% identical), RNY1P15 (81% identical), and 99 more.